MET (MET proto-oncogene, receptor tyrosine kinase)
Diseases named in the same sentence as MET in open-access papers (continued):
Sharing a sentence is not in itself a finding about the gene and the disease.
tumor (continued). "Through the high affinity for tumor cell-specific antigens, the drug is transported to tumor lesions with a high expression of c-MET." (PMID 34575576, 2021). "ARGX-111 is the first anti-MET agent to be generated capable of killing MET-expressing tumor cells in addition to blocking HGF/MET signaling." (PMID 34200749, 2021). "Crizotinib, a MET inhibitor, has been also studied in combination with axitinib, showing decrement in vascularity density along with suppressed tumor growth." (PMID 34885091, 2021). "The full range investigative strategy unveiled new insights into the therapeutic prospect of targeting c-MET/PI3K in tumor hypoxia." (PMID 33859738, 2021). "A prognostic biomarker (HER2; BRAF V600E mu­tations; RET gene rearrangements; high-level MET amplification) is indicative of patient survival independent of the treatment received because the biomarker is an indicator of the innate tumor aggressiveness." (PMID 34660150, 2021). "We identified LuCaP 93 and LuCaP 173.1 as PDX models that would differentiate the response of a MET+/RET+ tumor from a MET-/RET- tumor to cabozantinib treatment." (PMID 33471819, 2021). "Binding of HGF to c-MET activates the tyrosine kinase activity of c-MET, which promotes the proliferation, metastasis, and invasion of various tumor cells." (PMID 34408780, 2021). "Among the 35 available tumor samples, 45.7% (16/35) were identified as MET focal amplification by NGS." (PMID 34758872, 2021). "The FISH analysis in the 155 MM samples showed that the average MET-gene copy number (MET-GCN)/tumor cell varied between 1.44 and 5.69." (PMID 34884673, 2021). "In animals bearing LuCaP 93 tumors, cabozantinib treatment significantly decreased tumor volume (TV) in MET+/RET+ LuCaP 93 animals compared to vehicle controls (p = 0.0175)." (PMID 33471819, 2021). "Following results from Phase 1b, Phase 2 investigated the efficacy and safety of tepotinib dosed at 500 mg QD in patients with HCC tumours with MET overexpression who had previously been treated with sorafenib." (PMID 33824476, 2021). "Exosomal circ‐PDE8A derived from plasma of PDAC patients has been reported to promote tumor invasion by upregulating MET (MET proto‐oncogene, receptor tyrosine kinase)." (PMID 34766148, 2021). "Aberrant c-MET pathway activation plays an important role in tumorigenesis as it promotes tumor cell growth, survival, migration, and invasion, as well as tumor angiogenesis." (PMID 35076580, 2021). "We found that miR-34a-5p acts as a tumor suppressor, directly represses the proto-oncogene MET, and modulates cell proliferation." (PMID 33596979, 2021). "Although in contrast to previous reports, very low c-MET expression was detectable in in vitro 4T1 cell lysates as well as in vivo primary tumor lysates on western blot (and immunohistochemistry)." (PMID 33731699, 2021). "The analysis presented in the study indicates that assessment of MET mRNA from the tumour bulk is useful but that it is only whenever assessment of the protein is also considered do you see patients with genuinely MET‐addicted malignancy." (PMID 34428346, 2021). "IRCR201 is a human IgG1 bivalent antibody, which induces rapid depletion of MET protein via the lysosomal degradation pathway and inhibits tumor growth in vitro and in vivo." (PMID 34925346, 2021). "MET detection in all tumor cells from more than 50% of the cases agreed with previous reports that showed MET protein overexpression in approximately 45% of ESCC samples, indicating that MET is a potential therapeutic target for ESCC patients." (PMID 34037097, 2021). "In the PE/CA-PJ15 cell line the c-MET inhibitor significantly reduced primary tumor growth and even more decreased hepatic colonization." (PMID 34257586, 2021).
tumor (continued). "In each group, MET-expression status and MET-GCNG/GA had been assessed by IHC and FISH on diagnostic biopsies with >50% of tumor cell content." (PMID 34884673, 2021). "Taken together, these data support the mechanistic connection of miR-34a-5p in suppressing oncogenic MET and restoring tumor immunity through targeting PDL1." (PMID 33596979, 2021). "One-week post-resection, mice were randomised to four treatments of 8 weeks: (i) IgG, (ii) gemcitabine (G), (iii) HGF/c-MET inhibition (HiCi) and (iv) HiCi + G. Tumour burden was assessed longitudinally by bioluminescence." (PMID 34199452, 2021). "Our interrogation of bulk and single-cell transcriptomes from clinical GBM specimens also supports the involvement of c-MET signaling in invasive tumor behaviors." (PMID 33859738, 2021). "The mean percentage of positive tumor cells for c-MET, RhoA, and CLDN18 expression was 16.2% (SD ± 24, mean H-score = 20.7 ± 36.8), 36.2% (SD ± 30), and 35.0% (SD ± 29.9), respectively." (PMID 35076580, 2021). "Tumor-associated genes on Chr9q such as FANCC, NTRK2, SYK, and NOTCH1 were amplified; amplification of BRAF, EZH2, MET, CDK6 and HGF located on Chr7 were also detected." (PMID 34895266, 2021). "Since the knockdown of c-MET suppressed LC tumor growth and cell migration under a DNM3 depletion condition, the c-MET inhibitor CZT was investigated for its antitumor potential." (PMID 34490234, 2021). "A total of 17 ESCC patients (77.3%) showed positive MET immunostaining in the cell membrane, from which 12 (54.5%) showed positivity in 100% of the tumor cells." (PMID 34037097, 2021). "For instance, in squamous cell carcinoma, inhibition of Twist1 was required for MET to initiate tumor growth at a secondary site." (PMID 33996581, 2021). "Tumor c-MET levels (total and phosphorylated) were determined in paired biopsies before and after 7 days of pazopanib treatment." (PMID 34180036, 2021). "ARGX-111 combines complete blockade of this pathway with enhanced tumor cell killing and was investigated in 24 patients with MET-positive advanced cancers in a phase 1b study at four dose levels (0.3–10 mg/kg)." (PMID 34200749, 2021). "CircPDE8A can promote the growth of tumor cells by upregulating the expression of MET (one of the key oncogenes of epithelial tumors)." (PMID 34360530, 2021). "Mechanistic study showed that circBFAR promoted expression of MET through sponging tumor suppressive miR-34b-5p, leading to the activation of MET/PI3K/Akt signaling." (PMID 34439315, 2021). "The major aims were to determine the clinical safety of ARGX-111 in patients bearing tumors overexpressing the MET protein and/or harboring MET amplification, pharmacokinetics, pharmacodynamics and preliminary evidence of anti-tumor activity." (PMID 34200749, 2021). "Six overexpressed and mutated tumor antigens associated with poor prognosis and infiltration of antigen presenting cells were identified in PAAD, including ADAM9, EFNB2, MET, TMOD3, TPX2, and WNT7A." (PMID 33648511, 2021). "In breast tumors, clinical studies have correlated activation of the HGF pathway (as defined by c-MET over-expression) with increased tumor size, high tumor grade, and distant metastasis." (PMID 34344422, 2021). "We found that the HGF/c-MET pathway affected the tumor microenvironment mainly by interfering with expression levels of other genes." (PMID 34261467, 2021). "SU11274, an ATP-competitive inhibitor of c-MET, significantly inhibited tumor growth in a LoVo xenograft mouse model." (PMID 33466394, 2021). "Third, despite developing EGFR-TKI resistance, the tumor/s of patients detected with concurrent EGFR mutation and MET amplification at disease progression have acquired “addiction” to MET but remains “addicted” to EGFR." (PMID 34660287, 2021). "The study employed the use of genetic analysis in 53 pediatric GBMs as well as in five in vitro tumor model systems and reported a previously unidentified MET oncogene-affiliated gene fusion in approximately 10% of cases." (PMID 34055785, 2021).
tumor (continued). "As it has previously been shown that activated MET induces tumor invasion via phosphorylation of STAT3, we assessed levels of phospho-STAT3 (p-STAT3) and found decreased p-STAT3 after the introduction of miR-34a-5p mimic in CAL27 cell lines." (PMID 33596979, 2021). "QRT-PCR analysis demonstrated that TNS1 and MET were significantly up regulated in all EOCRC tumor samples." (PMID 34083590, 2021). "In both HCT116 and Caco-2 cells, LMWF enhances the suppressive effects of 5-FU on tumor cell migration through treatment through the c-MET/MMP-2 signaling pathway." (PMID 34360807, 2021). "VEGF promotes angiogenesis in GBM but also suppresses tumor cell invasion through a MET/VEGFR2 heterodimerization." (PMID 34806012, 2021). "MET expression/activation strongly correlates with the malignant grade of the tumor, as well as with the prognosis of the disease." (PMID 34298732, 2021). "In order to further analyze the regulatory role of c-Met expression level on glucose metabolism, we grouped tumor tissue samples into quartiles according to their MET expression levels to compare the four distinctive groups." (PMID 34059694, 2021). "Genomic studies in almost all types of human tumors show aberrations in several RTKs associated with tumor development and progression such as EGFR, HER2/ErbB2, MET, etc.." (PMID 33918490, 2021). "We find that in TNBCs with mesenchymal signatures, MET participates in a compensatory interplay with FGFR1 to regulate tumour-initiating cells (TICs)." (PMID 33772015, 2021). "The reduced c-MET turnover causes sustained c-MET activation and hence promotes proliferation and metastasis of tumor cells." (PMID 34065983, 2021). "The maximum tolerated dose (MTD) was determined to be 570 mg/m2 administered once a week and showed significant anti-tumor activity in MET-amplified non-small cell lung carcinoma patients." (PMID 34055785, 2021). "HGF-sustained MET-activation in cancer cells exacerbates their aggressiveness, prompting dissemination from the primary tumor to regional and distant sites." (PMID 34298732, 2021). "NGS genomic profiling of the operative tumor specimen revealed MET amplification that confirmed a rapid PR within 2 months." (PMID 35693217, 2021). "The activation of MET and its downstream signaling pathway involved in a number of important biological activities, including tumor cells growth, proliferation and metastasis." (PMID 34123778, 2021). "The lncRNA XIST serves as a miR-34a ceRNA via competing with MET for miR-34a binding and thus promoting cancer cell proliferation and tumor growth through upregulated MET–PI3K–AKT signaling." (PMID 33763422, 2021). "MET also regulates a variety of distinct biological processes characteristically exploited by tumours, including cell scattering, epithelial remodelling, cell proliferation and cell survival." (PMID 33772015, 2021). "MET activation has been shown to promote tumor cell growth, survival, migration, and invasion by interacting with multiple pathways." (PMID 34758872, 2021). "Whereas primary MET amplification is a low‐frequency event that occurs in around 1% to 5% of tumor cell clones, higher frequencies of MET amplification are found in patients with advanced and/or recurrent tumors." (PMID 33675179, 2021). "Taken together, these findings suggest that the c-MET/EGFR system is an important mediator within the tumor microenvironment (TME) that results in enhanced tumor growth." (PMID 34512327, 2021). "In the present study, 22 paired tumor and non-tumor normal tissue were examined for mRNA expressions of MET and ERBB2." (PMID 34335943, 2021). "Next, we assessed MET expression in samples obtained from different tumor regions of five patients, including superficial and profound biopsies." (PMID 34037097, 2021).
tumor (continued). "In in-vitro models, tumor cells that had the c-MET (a mesenchymal marker) gene silenced showed decreased invasive capabilities, which suggests that the mesenchymal subtype's prognosis is linked to the tumor's metastatic potential." (PMID 33500708, 2021). "PDAC is characterised by a strong tumour stromal proliferative response, and the HGF/MET pathway is involved in the signal transmission interaction between tumour and stromal cells." (PMID 33816276, 2021). "MET inhibition led to sustained tumor regression, and Western blot analysis revealed that MET inhibition alone induced up-regulation of the proapoptotic Bcl2-like protein 11 (BIM) in the tumor xenografts." (PMID 34516823, 2021). "KRAS amplification was implicated as the mechanism of resistance from crizotinib treatment in MET exon 14 mutant-NSCLC in a study using patient tumor-derived cells and xenografts, which was effectively targeted by dual MET/PI3K inhibition." (PMID 34660287, 2021). "Of these, only patients with high MET RNA‐ISH/low c‐MET IHC protein expressing tumours were found to be twice as likely to die of a colorectal‐specific death in 5 years." (PMID 34428346, 2021). "Compelling evidence indicates that CXCR4 regulates tumor EMT together with the c-MET signaling pathway." (PMID 34568309, 2021). "We next assessed mutant EGFR and total MET transcript expression in a series of EGFR-mutant patient tumor specimens through quantitative RT-ddPCR." (PMID 34516823, 2021). "Extensive experimental and clinical data provide several lines of evidence that HGF and its cognate receptor MET are crucial components of various diseases including organ fibrosis and tumor progression." (PMID 34128105, 2021). "Rather, it is the patient subgroup with high MET RNA‐ISH/low c‐MET IHC protein expressing tumours that would most likely benefit from MET inhibition." (PMID 34428346, 2021). "Other emerging biomarkers which are under investigation are PIK3CA mutations, high level MET amplification, ERBB2 mutation, and Tumor Mutational Burden (TMB)." (PMID 34440689, 2021). "Targeting of constitutively active MET by means of inhibitors is useful to blunt tumor growth in experimental models and in patients." (PMID 34925346, 2021). "We leveraged our finding that TRIM24 directly activates Met expression and TRIM24COE tumor-derived primary cells to test the potential of therapeutically targeting MET." (PMID 34508101, 2021). "The MET pathway, aberrantly activated particularly in type 1 PRCC, is associated with tumor growth, angiogenesis, and promotion of metastases, as well as treatment resistance." (PMID 34359706, 2021). "Altiratinib (a novel balanced inhibitor of MET/TIE2/VEGFR2) combined with bevacizumab reduced tumor volume, invasiveness, factor VIII-positive MVD, and Tie2+F4/80+ macrophage infiltration more effectively than bevacizumab alone." (PMID 34209679, 2021). "On the other hand, MET was found consistently upregulated in ESCC compared to non-tumor surrounding tissue, with median fold-changes of 5.96 (GSE20347), 3.83 (GSE45670), 6.02 (GSE75241), and 5.0 (our dataset)." (PMID 34037097, 2021). "By examining these genes via ingenuity pathway analysis, tenascin C emerged as a promising candidate linking MET signaling and tumor microenvironment." (PMID 34298732, 2021). "The IHC results were scored according to the staining intensity and per cent of tumour cells stained, and clinical samples were classified as having high or low c-MET expression." (PMID 33816276, 2021). "The anti-tumour efficacy of SHR-A1403 was further confirmed in a PDAC xenogeneic model with high expression of c-MET." (PMID 33816276, 2021). "As a MET kinase inhibitor, PLB-1001 had remarkable potency in selectively inhibiting MET-altered tumor cells in preclinical models and clinically achieved partial response in some advanced secondary GBM patients (NCT02978261)." (PMID 34671307, 2021).
tumor (continued). "Consistent with previous research, MET is involved in the crosstalk between tumor cells and tumor microenvironment." (PMID 33869254, 2021). "EGFR T790 M was detected in plasma, and MET amplification was found in the tumor at the time of resistance to afatinib." (PMID 34397683, 2021). "In the presence of EGFR inhibitors, the tumor cells respond with MET amplification, which allows the maintenance of hyperactivated cancer pathways, leading to tumor progression despite EGFR TKI treatment." (PMID 33153004, 2020). "The tumor level of MET and p-AKT had the same trend that the lowest level of MET and p-AKT in the sh-TUG1 plus 2 Gy group." (PMID 31918742, 2020). "A number of publications have reported that several micro-RNAs (miRNAs) inhibit tumor progression by targeting MET." (PMID 32435640, 2020). "Suppression of tumour invasion and metastasis by concurrent inhibition of c-MET and VEGF signalling (using cabozantinib) in pancreatic neuroendocrine tumours was also demonstrated by Sennino and colleagues." (PMID 33271944, 2020). "Aberrant c-MET activity can contribute to acquired tumor cell resistance to treatment with epidermal growth factor receptor (EGFR) targeting tyrosine kinases (TKIs) such as erlotinib." (PMID 32117721, 2020). "Activation of c‐MET increases tumour cell survival through the initiation of the DNA damage repair pathway." (PMID 32686903, 2020). "c-MET silencing in neutrophils resulted in increased tumor growth in mice, demonstrating c-MET positive neutrophils have anti-tumor properties." (PMID 32117721, 2020). "MET protein overexpression has been reported in 20–37% of tumor tissues, and MET gene amplification in 5–26% of NSCLC patients with EGFR inhibitor resistance." (PMID 31948451, 2020). "The interaction between the HGF/c-MET pathway and anti-tumour immune-response is complex and yet to be fully understood." (PMID 33396187, 2020). "Recent studies showed the role of miR-144 as a tumor suppressor by targeting tyrosine-protein kinase Met (c-MET)." (PMID 32276343, 2020). "Since the HGF/MET signaling pathway plays a crucial role in tumor progression, the design of new antibodies and inhibitors considering different perspectives is of great value for improving the efficacy of MET-targeted drugs." (PMID 32435640, 2020). "Our in vitro and in vivo studies strongly supported the clinical evaluations of tepotinib, which prevented the EMT and tumor growth in c-MET- and MUC5B-expressing GCs." (PMID 32825724, 2020). "The MET signalling pathway is involved in processes of tumourigenesis, such as tumour proliferation, protection from apoptosis, angiogenesis, and motility." (PMID 32295618, 2020). "Inhibition of MET can have potent anti-tumor effects, including regression of human glioblastoma tumor xenografts." (PMID 31776899, 2020). "Collectively, these results suggest that tepotinib suppresses tumor growth and migration by negatively regulating c-MET-induced EMT." (PMID 32825724, 2020). "We optimized the ddPCR assay using DNA isolated from a panel of cell lines representative of different levels of MET amplification and different cancer tumor types (lung, colon, prostate, skin, breast, and gastric)." (PMID 32102486, 2020). "Aberrantly activated c-MET can drive tumorigenesis, leading to aggressive cancer phenotypes and poor prognosis by promoting tumor cell survival, migration, EMT, and treatment resistance." (PMID 32825724, 2020). "Target 2, which resided 1.06 mm from target 1, exhibited tumor cells containing both strongly amplified MET and CCND1, 3 to 4 copies of EGFR, 3 to 4 copies of FGFR2, and loss of both copies of the genes encoding PD-L1/PD-L2." (PMID 32338752, 2020). "Cabozantinib (CBZ) hinders the activation of multiple receptor tyrosine kinases involved in tumor angiogenesis, such as hepatocyte growth factor receptor (MET) and vascular endothelial growth factor receptor 2 (VEGFR2)." (PMID 32655941, 2020).